KLK2 (kallikrein related peptidase 2)
Diseases named in the same sentence as KLK2 in open-access papers (continued):
Sharing a sentence is not in itself a finding about the gene and the disease.
male infertility (1 paper, 2020). The inability of the male to effect fertilization of an ovum after a specified period of unprotected intercourse. "Lee and Lee performed genotypic association analysis in 218 non-obstructive azoospermic and 220 fertile controls and showed that a SNP in the KLK2 intron 1 (+255 G > A, rs2664155) was associated with male infertility." (PMID 32529252, 2020).
metastatic disease (1 paper, 2024). "In the present study, the PrC-specific markers PSA, PSMA, and KLK2 were only detected in blood samples from patients with metastatic disease, but not with early localized PrC." (PMID 39305397, 2024).
Renal clear cell carcinoma (1 paper, 2018). "Renal clear cell carcinoma had six KLKs in which increased expression was associated with overall survival (KLK2: HR = 1.69; KLK4: HR = 1.63; KLK8: HR = 1.71; KLK10: HR = 2.12; KLK11: HR = 1.76; and KLK14: HR = 1.86)." (PMID 29707153, 2018).
thyroid cancer (1 paper, 2018). "In addition, thyroid carcinoma displayed significant downregulation of KLK2 (13-fold) and KLK4 (9-fold)." (PMID 29707153, 2018). "Also, our ROC analysis indicates that KLK2 and KLK4 can be used as novel biomarkers for thyroid cancer, since previous studies have not reported any kallikreins as biomarkers for thyroid cancer." (PMID 29707153, 2018).
uterine corpus endometrial carcinoma (1 paper, 2018). A endometrial carcinoma (disease) that involves the body of uterus. "Furthermore, uterine corpus endometrial carcinoma displayed significant overexpression of KLK12 (3-fold) and downregulation of KLK1 (5-fold), KLK2 (4-fold) and KLK4 (6-fold)." (PMID 29707153, 2018).
tumor (43 papers, 2008 to 2026). "We describe the immunologic microenvironment on PRAD tumors with a high expression of KLK2, including a gene signature linked with an inert immune microenvironment, that predicts the response to ICIs in other tumor types." (PMID 38396898, 2024). "The enzyme’s activity may contribute to tumor growth and metastasis, positioning KLK2 as both a diagnostic marker and a potential target for immunotherapeutic approaches, including CAR-T cells." (PMID 41153826, 2025). "In mCRPC samples, a significant proportion of metastatic tumor tissue sites coexpressed KLK2 and PSMA (54% in bone and 61% in lymph nodes)." (PMID 40627156, 2025). "Tumor regression was accompanied by KLK2 CAR T-cell expansion and cytokine release, consistent with the functionality of KLK2 CAR T cells after tumor antigen exposure in vivo." (PMID 40627156, 2025). "Treatment of VCaP tumor–bearing mice with a single i.v. injection of 225Ac-KLK2 reduced tumor growth across multiple doses, with 110% TGI achieved at 500 nCi compared with control." (PMID 40627156, 2025). "As compared with VCaP tumors from null × CD3–treated mice, KLK2 × CD3 treatment resulted in increased CD8+ and CD4+ T-cell infiltration, with a concomitant reduction of KLK2+ tumor cells as measured by the detection of KLK2 and cytokeratin." (PMID 40627156, 2025). "Factor 5 exhibits the highest signal in tumour regions, encompassing both Gleason 3 and Gleason 4 areas, accompanied by high expression of KLK2 and KLK3, which are markers of prostate glandular epithelium." (PMID 40167331, 2025). "This is a bispecific antibody that can simultaneously target kallikrein 2 (klk2) on the surface of tumor cells and CD3 on the surface of T cells." (PMID 41281744, 2025). "Among the most promising candidates is JNJ-78278343, a bsAb designed to targets KLK2 on tumor cells and the CD3 receptor complex on T cells." (PMID 41153826, 2025). "Accordingly, KLK2 was targeted with bispecific T-cell engagers that resulted in tumor cytotoxicity and with an α-radioconjugate 225Ac-anti-KLK2-mAb, which had anti-tumor activity in a xenograft model, similar to CAR-T cells." (PMID 41516101, 2025). "KLK2, one of the genes whose expression was most significantly decreased by α-mangostin, plays a role in carcinogenesis and tumor metastasis, and it was recently revealed that high KLK2 expression correlates with PCa severity and aggressiveness." (PMID 37046780, 2023). "These patient samples also exhibited high tumor:normal AR enrichment at the widely studied AREs near KLK2 and KLK3 suggesting higher overall AR binding." (PMID 34409300, 2021). "LvCaP-1 expressed NKX3-1, HOXB13 (mutated G84E), FOLH1, KLK2, and KLK3, but with only a low level of PSA secretion (i.e., serum PSA of 1.4 ± 0.4 ng/mL/g tumor)." (PMID 33724955, 2021). "AR can modulate the expression of TFs, biomarkers and vital tumour promoters in PrCa development, such as KLK2, KLK3, MYC, MSMB and TMPRSS2." (PMID 32397189, 2020). "The repression effects on AR expression can actually reduce its function; moreover, QRC inhibited PSA and KLK2 secretion, two proteins known as androgen-regulated tumor markers." (PMID 28239427, 2017). "PSA and KLK2 can indirectly regulate tumor cell growth, tumor invasion, and osteoblastic metastasis." (PMID 28239427, 2017). "Nonetheless, other antigens such as STEAP1/2, KLK2, EpCAM, B7-H3, nfP2X7, NKG2DL, F77 are emerging as promising candidates for CAR-T cell therapy, as they are predominantly expressed in PCa and associated with tumor proliferation and immune evasion." (PMID 41153826, 2025). "In addition, KLK2 levels correlate with disease severity, and KLK2 has been reported to facilitate tumor growth and metastasis through several mechanisms, including activation of growth factor and mitogenic pathways." (PMID 40627156, 2025). "In line with this, we did not observe any association between KLK2 expression and Gleason score or tumor grade, or the presence of lymph nodes (N1)." (PMID 38396898, 2024).
tumor (continued). "KLK2 is involved in multiple proteolytic cascades that influence tumor growth and metastasis." (PMID 37593117, 2023). "Further, tumor-derived platelets biomarkers, as KLK3, FOLH1, and NPY, enable prediction after abiraterone therapy in castration resistant prostate cancer (CRPC) and KLK2, KLK3, and FOLH1 were associated with short OS." (PMID 33673461, 2021). "Notably, targeting KLK2 with three different MoAs, including bispecific T-cell redirector, targeted α-radioligand, and autologous chimeric antigen receptor T cells, showed potent in vitro activity and robust in vivo tumor control." (PMID 40627156, 2025). "Analysis of GSE99671 revealed significantly higher expression levels of KLK2, NRXN1, HES5, OR2W3, and HS3ST4 in normal samples compared to tumor samples." (PMID 40128298, 2025). "In xenograft mouse models, KLK2 × CD3 and KLK2-targeted CAR T cells exhibited antitumor activity accompanied by CD4+ and CD8+ T-cell tumor infiltration." (PMID 40627156, 2025). "Representative micrographs of CD8, CD4, KLK2, and pan-cytokeratin immunostaining of tumor samples collected at day 50 (end of study) from the null × CD3 and KLK2 × CD3 15 mg/kg treatment groups are shown." (PMID 40627156, 2025). "Cell surface expression of KLK2 was confirmed by FACS of VCaP cells and dissociated mCRPC tumor cells." (PMID 40627156, 2025). "KLK2 and KLK3/PSA participate in extracellular matrix degradation, activation of protease-activated receptors, in particular of PAR-2, tumor invasion, angiogenesis, and proliferation." (PMID 41516101, 2025). "For example, cancer RNA biomarkers such as KRAS, PCA3, PIK3CA mutants, EGFRvIII, FOLH1, KLK2, KLK3, EML4-ALK, and NYP have been reported to be sequestered by platelets that actively uptake tumor-derived material." (PMID 39274207, 2024). "The combination of KLK2 and ARA70 can reduce G1 arrest of tumor cells and promote tumor proliferation by regulating p21/cdk2/cyclin D1 signaling pathway." (PMID 37593117, 2023). "In a deeper examination of the tumor tissue, we observed a considerable decrease in the mRNA expression levels of PSA and KLK2 - known target genes of AR - in response to the combined therapy of YIV-818-A and enzalutamide." (PMID 37860121, 2023). "And combination of KLK2 and ARA70 can also inhibit tumor cell apoptosis and promote tumor progression by bax/bcl2/caspase-3 signaling pathway." (PMID 37593117, 2023). "The novelty of the current study lies in the fact that we tried to modulate the genes KLK2, KLK4, KLK6, and KLK14 to inhibit the progression of PCa via miR-378, which can be produced in tumor cells through EPA, stimulating co-expression of the gene PGC-1β." (PMID 35681793, 2022). "Herein we report a technology platformbased on novel activity-based probes (ABPs) and inhibitors enablingsimultaneous orthogonal analysis of KLK2, KLK3, and KLK14 activityin hormone-responsive PCa cell lines and tumor homogenates." (PMID 34085829, 2021). "(D) qRT-PCR analysis of DECR1 and androgen regulated genes KLK2 and KLK3 mRNA expression in a cohort of 10 patient-derived human prostatic ex vivo tumor explants treated with enzalutamide (ENZ, 10 μM)." (PMID 32686647, 2020). "It binds both CD3 receptors on T cells and KLK2 on the surface of tumor cells and exhibits significant anti-tumor activity without adverse effects." (PMID 41516101, 2025). "When GLP was used in combination with flutamide and docetaxel, it could significantly down-regulate the expression of genes related to tumor progression, including OPN, VEGF-c, snail, E-cadherin, and KLK2." (PMID 40507156, 2025). "The median H-scores of KLK2, KLK4, KLK6, and KLK14 protein expression in the nuclei of normal cells were 9, 24, 12.5, and 14.5, respectively, as compared with the tumor cells (42, 73.5, 43.5, and 62, respectively); therefore, the p values were 0.0027, 0.0009, 0.0062, and 0.0009, respectively." (PMID 35681793, 2022).
tumor (continued). "KLK2 expression was significantly decreased in recurrent tumor tissues compared with non-recurrent tissues (P = 0.021), and in non-recurrent tissues compared with healthy tissues (P = 0.026)." (PMID 33150763, 2020). "These exciting therapeutic developments in targeting PSMA, KLK2, STEAP1, and PSCA in mCRPC have opened tremendous opportunities for sequencing treatment targeting the same tumor surface antigens with different strategies or different tumor surface antigens with the same or different strategies." (PMID 39272956, 2024). "Notably, within these early-passage organoids we identified a population fitting our profiling of ERG+ tumor cells, expressing a high level of LE cell markers (KLK3, KLK2, and ACPP) and tumor markers (PCA3, TRPM8, and ERG), which we annotated as putative tumor cells." (PMID 35013146, 2022). "The levels of KLK2, 9, and 14 gene transcripts were not altered in tumor samples." (PMID 34065672, 2021). "Identification of seven genes (MYLK, KLK2, KLK3, HAN11, LTF, CSRP1, TGM4) which have their connectivity altered between normal/tumoral conditions may provide novel insights into specific targets against tumor progression." (PMID 19055846, 2008). "ERG+ and ERG− tumor cells and non-malignant LE cells all showed high expression of luminal markers KLK3, KLK2, and ACPP35." (PMID 35013146, 2022). "Interestingly, serine type peptidase such as KLK2 (boxed in orange) are reported to activate plasminogen activator which plays important role in extracellular matrix (ECM) degradation suggesting that these lncRNAs may down-regulate serine-type peptidase so that tumor capsule can remain intact." (PMID 32636408, 2020). "Given that tumor cells predominantly express LE cell markers such as KLK2, KLK3, ACPP, and NKX3-1, clusters with high LE signatures scores could be either tumor cells or non-malignant LE cells." (PMID 35013146, 2022). "Additionally, in a first-in-human phase 0 study, we previously reported that the indium-111 (111In)–labeled anti-KLK2 monoclonal antibody, [111In]-DOTA-h11B6, demonstrated tumor localization by selectively targeting mCRPC lesions with nominal uptake in healthy organs." (PMID 40627156, 2025).
cancer (31 papers, 2009 to 2026). A tumor composed of atypical neoplastic, often pleomorphic cells that invade other tissues. "The exon involved in this event encodes for a protein domain essential for the interaction with KLK2 encoded proteins, which in turn is found aberrantly expressed and is used as a prognostic biomarker in many cancer types, including BCs." (PMID 35887187, 2022). "Tissue KLKs, especially KLK2, are promising targets for therapy in advanced PCa because of their high PCa specificity and their correlation to the rising cancer grade and stage." (PMID 41531507, 2026). "Other KLKs have emerged as key players in PCa pathogenesis, particularly KLK2, KLK4, and KLK14, which are implicated in cancer progression through protease activity, AR modulation, and interaction with extracellular matrix components." (PMID 41531507, 2026). "PAR is G-protein-coupled receptor (GPCR) and KLK2 is a potentially important activator of this receptor and cancer-related mediators." (PMID 37593117, 2023). "Tissue kallikrein 2 (KLK2) is a kind of serine protease, and has a close relationship with the occurrence and development of malignant tumors." (PMID 37593117, 2023). "Yet, the mapped genes were highly relevant to PCa etiology and included known cancer drivers LDLRAD4, GMNN, COL1A1, CD38, PTPRN2, GTSE1 and CAMK2N1 in the risk signature and KLK2, AR, KLK3, SPDEF in the relapse signature." (PMID 33845808, 2021). "Logistic regression analyses were conducted to determine the significance of KLK2 SNPs and hK2 levels for predicting cancer at repeat biopsy." (PMID 25279276, 2014). "In addition, KLK2 is capable of activating the zymogen form of uPA, a crucial extracellular protease correlated with cancer invasion and metastasis." (PMID 41531507, 2026). "KLK2 has a variety of physiological functions, involved in physiological adaptation, physiological metabolism and regulation of brain development, and has a close relationship with the occurrence of a variety of malignant tumors." (PMID 37593117, 2023). "Human kallikrein 2 (KLK2), a possible serum marker for PCa may play a role in cancer progression and metastasis." (PMID 23708103, 2013). "To further explore the role of KLK2 in PRAD, we analyzed KLK2 gene expression using the TCGA (The Cancer Genome Atlas) repository through a resource termed UALCAN." (PMID 38396898, 2024). "Our data show strong evidence that proves that increasing the expression level of miR-378 in cells by EPA induces the PGC-1β gene, which possibly affects KLK2, KLK4, KLK6, and KLK14 gene expression in cancer cells." (PMID 35681793, 2022). "Among its related pathways are Transcriptional misregulation in cancer and Activated PKN1, which stimulates transcription of AR (androgen receptor) regulated genes KLK2 and KLK3." (PMID 33613644, 2021). "Known cancer genes such as EGFR, EZH2, or CCDN2 were frequently affected by duplications and other known cancer genes such as CDKN2A, RB1, KLK2, or CD79A were frequently affected by deletions." (PMID 32604718, 2020). "As can be inferred from the array signal intensity levels, expression of the major functional prostatic secretory proteins ACPP, AZGP1, KLK2, KLK3, and MSMB was down-regulated in the cancer cells compared to the luminal cells." (PMID 20021671, 2009). "Free, intact and total PSA, and kallikrein-related peptidase 2 were measured in cryopreserved blood from 6129 men with elevated PSA (≥3.0ng/mL) participating in the prospective, randomized trial Prostate Testing for Cancer and Treatment." (PMID 25863334, 2015). "Kallikrein-2 (KLK2) is a member of the Kallikrein superfamily of serine proteases, which are considered putative biomarkers for the screening, diagnosis, prognosis, and monitoring of various cancers including those of the prostate, ovaries, breast, testicles, and lung." (PMID 24708840, 2014).
cancer (continued). "This demonstrated that EPA could significantly induce PCa cell death by down-regulating the KLK2, KLK4, KLK6, and KLK14 genes in PCa cells, then triggering apoptosis in the cancer cells; however, a similar mechanism did not affect the normal cells." (PMID 35681793, 2022). "Thus, while its expression synergisms with the ATP2B3 (ATPase, Ca++ transporting, plasma membrane 3) and KLK2 (kallikrein-related peptidase 2) in NOR are not modified by ccRCC, the antagonistic expression with the AP2A1 is switched to a synergistic one in all three cancer nodules." (PMID 38132440, 2023).
adenocarcinoma (2 papers, 2004 to 2018). A common cancer characterized by the presence of malignant glandular cells. "Kallikreins are being investigated as potential serum markers for adenocarcinomas such as prostate (KLK2), breast (KLK10, 12, 13) and ovary (KLK6, 8, 10, 11)." (PMID 14760385, 2004).
hematologic malignancies (1 paper, 2024). "We first studied the expression of KLK2 across a wide number of solid tumors and hematologic malignancies using publicly available human genomic datasets, as described in the materials and methods section." (PMID 38396898, 2024).
KLK2 also shares sentences with these, for which no sentence is quoted: ovarian carcinoma (3 papers); neuroendocrine carcinoma (2); benign prostate hyperplasia (1); colon adenocarcinoma (1); gastrointestinal stromal tumor (1); hepatocellular carcinoma (1); hereditary prostate cancer (1); invasive carcinoma (1); lymphoma (1); metastatic prostate carcinoma (1); papillary renal cell carcinoma (1); prostatitis (1); renal carcinoma (1); small cell lung carcinoma (1); urothelial bladder carcinoma (1).